ATP5MC1 (ATP synthase membrane subunit c locus 1)
Description:
Subunit c, of the mitochondrial membrane ATP synthase complex (F(1)F(0) ATP synthase or Complex V) that produces ATP from ADP in the presence of a proton gradient across the membrane which is generated by electron transport complexes of the respiratory chain (Probable). ATP synthase complex consist of a soluble F(1) head domain - the catalytic core - and a membrane F(1) domain - the membrane proton channel. These two domains are linked by a central stalk rotating inside the F(1) region and a stationary peripheral stalk. During catalysis, ATP synthesis in the catalytic domain of F(1) is coupled via a rotary mechanism of the central stalk subunits to proton translocation (Probable). With the subunit a (MT-ATP6), forms the proton-conducting channel in the F(0) domain, that contains two crucial half-channels (inlet and outlet) that facilitate proton movement from the mitochondrial intermembrane space (IMS) into the matrix. Protons are taken up via the inlet half-channel and released through the outlet half-channel, following a Grotthuss mechanism.
Synonyms: ATP5G1; ATP5A; ATP5G
Tractability: Small molecule: a structure with a bound ligand is known. Antibody: UniProt predicts a signal peptide or a membrane-spanning region. PROTAC: ubiquitination databases record sites on it.
Gene: Protein-coding gene on chromosome 17 (48,892,765 to 48,895,875, forward strand). Ensembl gene ENSG00000159199.
Subcellular location: Mitochondrion membrane
Pathways (Reactome):
Metabolism: Formation of ATP by chemiosmotic coupling
Organelle biogenesis and maintenance: Cristae formation
Protein localization: Mitochondrial protein import
Gene Ontology:
Molecular function: protein binding; proton channel activity; proton transmembrane transporter activity
Biological process: proton motive force-driven ATP synthesis; proton transmembrane transport
Cellular component: mitochondrion; proton-transporting ATP synthase complex; mitochondrial inner membrane; mitochondrial membrane; proton-transporting two-sector ATPase complex, proton-transporting domain
Genetic constraint (gnomAD): Loss-of-function variants: 4 observed, 12.66 expected, observed/expected ratio (o/e) 0.32, 90% interval 0.16 to 0.72. The upper end of that interval is the gene's LOEUF score, 0.72, which puts it in group 2 of 6, group 1 being the genes least tolerant of losing a copy. Missense variants: 117 observed, 175.56 expected, observed/expected ratio (o/e) 0.67, 90% interval 0.57 to 0.78. Synonymous variants: 52 observed, 64.94 expected, observed/expected ratio (o/e) 0.8, 90% interval 0.64 to 1.01.
Homologues: Orthologues: chimpanzee ATP5MC1 (100% identical), macaque ATP5MC1 (97% identical), pig ATP5MC1 (90% identical), guinea pig Atp5mc1 (88% identical), rabbit ATP5MC1 (88% identical). Paralogues in human: ATP5MC3 (72% identical), ATP5MC2 (70% identical).
Diseases named in the same sentence as ATP5MC1 in open-access papers:
ATP5MC1 is named in the same sentence as 28 diseases in open-access papers, as found by Europe PMC text mining. Sharing a sentence is not in itself a finding about the gene and the disease. The quoted sentences say what the papers report.
Parkinson’s (2 papers, 2023 to 2025). "However, together with NDUFB1, COX17, and ATP5MC1, they were reported as upregulated in patients with Parkinson’s, Alzheimer’s, and Huntington’s diseases." (PMID 41296444, 2025).
metabolic disease (2 papers, 2021). A congenital disorder (due to inherited enzyme abnormality) or acquired (due to failure of a metabolically important organ) disorder resulting from an abnormal metabolic process. "SNF8, UBE2Z, CALCOCO2, and ATP5MC1 have been shown a core function in metabolic disease and cancer." (PMID 35052342, 2021).
ATP5MC1 also shares sentences with these, for which no sentence is quoted: neuronal ceroid lipofuscinosis (3 papers); Batten disease (2); infection (2); insomnia (2); Alzheimer disease (1); asthma (1); atherosclerosis (1); breast carcinoma (1); breast tumor (1); cancer (1); clear cell renal cell carcinoma (1); colorectal cancer (1); depression (1); diabetic cardiomyopathy (1); energy metabolism disorder (1); fragile X syndrome (1); HCMV infection (1); Huntington disease (1); kidney damage (1); kidney disease (1); lysosomal disorders (1); myocarditis (1); neurodegenerative disease (1); papillary thyroid carcinoma (1); steatosis (1); tumours (1).